LRIT1 (leucine rich repeat, Ig-like and transmembrane domains 1)
Description:
Photoreceptor synaptic protein essential for normal vision (By similarity). Involved in synapse formation in cone photoreceptor cells (By similarity).
Synonyms: LRRC21; PAL; DKFZP434K091; FIGLER9
Tractability: Antibody: UniProt predicts a signal peptide or a membrane-spanning region.
Gene: Protein-coding gene on chromosome 10 (84,231,520 to 84,241,546, reverse strand). Ensembl gene ENSG00000148602.
Subcellular location: Endoplasmic reticulum membrane; Cell projection, dendrite
Subcellular location (Human Protein Atlas): Flagellar centriole
Gene Ontology:
Cellular component: endoplasmic reticulum membrane; dendrite; synapse; synaptic cleft
Genetic constraint (gnomAD): Loss-of-function variants: 25 observed, 24.68 expected, observed/expected ratio (o/e) 1.01, 90% interval 0.74 to 1.41. The upper end of that interval is the gene's LOEUF score, 1.41, which puts it in group 5 of 6, group 1 being the genes least tolerant of losing a copy. Missense variants: 837 observed, 796.3 expected, observed/expected ratio (o/e) 1.05, 90% interval 0.99 to 1.11. Synonymous variants: 361 observed, 339.08 expected, observed/expected ratio (o/e) 1.06, 90% interval 0.98 to 1.16.
Homologues: Orthologues: chimpanzee LRIT1 (98% identical), macaque LRIT1 (96% identical), pig LRIT1 (81% identical), mouse Lrit1 (79% identical), rat Lrit1 (79% identical), guinea pig LRIT1 (78% identical), rabbit LRIT1 (74% identical), dog LRIT1 (73% identical), tropical clawed frog lrit1 (49% identical), zebrafish lrit1a (49% identical), zebrafish lrit1b (49% identical), Drosophila melanogaster kek3 (17% identical), and 3 more. Paralogues in human: LRIT3 (34% identical), LRIG2 (20% identical), LRIG1 (19% identical), LRIG3 (19% identical), LGR5 (17% identical), LGR6 (16% identical), ELFN2 (15% identical), LGR4 (15% identical), TRIL (15% identical), LRRC24 (14% identical), CPN2 (13% identical), ELFN1 (13% identical), and 10 more.